CD4 (CD4 molecule)
Diseases named in the same sentence as CD4 in open-access papers (continued):
Sharing a sentence is not in itself a finding about the gene and the disease.
infection (continued). "Observations of CNS compartmentalized viral variants, assessed by viral genomic sequencing within the cerebrospinal fluid (CSF) showed ability to mediate infection of cells with lower levels of CD4, and longer half-lives post-acute infection." (PMID 38060615, 2023). "Subsequently, we investigated LAG3 expression on CD4+ T-cell subsets in the liver and spleen of mice after 24 weeks of infection." (PMID 37172058, 2023). "Altogether, these data demonstrate that ACE2, TMPRSS2, and CD4 are all required to allow the infection of CD4+ T cells by SARS-CoV-2." (PMID 37523305, 2023). "CTLA4 is a key modifier of CD4+ T-cell cytotoxicity, and the pathological CD4cyt phenotype is accentuated by infection." (PMID 37161048, 2023). "This rebounds with the flooding of CD4+ T cells into the brain due to severe infection as the immune system begins to recover and reawaken with antiretroviral therapy (ART)." (PMID 36902168, 2023). "After breakthrough infection, baseline CD4 counts were negatively correlated with HIV DNA and CA-RNA levels, respectively (r = −0.6077, p = 0.0013; r = −0.6408, p = 0.0006)." (PMID 38140668, 2023). "This hierarchy should restrict the development of the most potent, and hence risky, CD4 immune memory to infection with the most dangerous pathogens." (PMID 38152398, 2023). "Vehicle and VX-765-treated groups presented a slight but significant reduction of CD4+ T cells percentages and CD4/CD8 T cell ratio in the blood at day 22 post-infection." (PMID 36800238, 2023). "During an infection, antigen activated naïve CD4+ T cells differentiate into helper T cell (Th) subsets (Th1, Th2, T follicular helper (Tfh), Th17) that secrete various cytokines and facilitate a pro-inflammatory response." (PMID 36992265, 2023). "HIV-LucIND116A infection of POLE3 KD primary CD4+ T cells resulted in an increased (2.3- to 4.5-fold) type I IFN response compared to that in noninfected and HIV-1 IND116A-infected control CD4+ T cells." (PMID 37922361, 2023). "We observed a contraction at 10 months post-infection (median: 0.76% (p < 0.0001) for CD4 + T cells and 0.18% (p < 0.0001) and CD8 + T cells) after which the response remained stable throughout the 20-month follow-up period." (PMID 37974069, 2023). "Further, Nef+ HIV infections exhibited increased PS exchange, and a greater number of CD4-/CD62L- T cells than Nef- infections." (PMID 36780482, 2023). "At 20 months post-infection, where 99% of the participants had received at least one vaccine dose, the percentage of CD4 + S-specific memory T cells had only increased slightly compared to 1 month post-infection." (PMID 37974069, 2023). "For this, we treated CD4+ T cells from normal donors with the CDK8/19 inhibitors or a vehicle control prior to infection with the replication incompetent RGH dual-reporter virus." (PMID 37671866, 2023). "How quickly are these populations of productively and latently infected cells established, and do both populations arise from infection of activated CD4+ T cells, as just described?" (PMID 37733443, 2023). "LF survivors show virus-specific CD4 and CD8 T-cell responses during the acute phase of infection, which are associated with virus clearance and recovery." (PMID 36992218, 2023). "In a mouse model of latent Mtb infection, lung resident T cell subsets (CD44hiCD62LlowCD69+ and CD44hiCD62low CD4 T cells) and Ag85B-specific T cells remain significantly increased among infected mice for as long as 7 months after infection." (PMID 38130713, 2023). "The cellular immune responses in individuals with vaccine breakthrough infection target only the spike antigen, while the number of CD4+ T cells specific to the N protein is significantly higher in individuals with unvaccinated control infections." (PMID 38140214, 2023). "Like in SIV, we show that HIV can directly infect these resting CD4+ T cells to establish a self-propagating and expanding infection in Fiebig I as the prelude to systemic infection." (PMID 37733443, 2023).
infection (continued). "CD4 T cells are critical in the orchestration of both the antibody and cellular adaptive immune response to infections." (PMID 37841265, 2023). "It is likely that detection of larger amounts of antibody in infected women reflects compromised development of CD4 T cell responses that limit burden and duration of infection, leading to increased antigen exposure and subsequent antibody production." (PMID 37318345, 2023). "CD4+ T cells play a pivotal role in infection, inflammation, and autoimmunity through cytokine release, including IL-4, IL-13, and IL-17, which induces a cascade of reactions that act against allergens." (PMID 36980282, 2023). "Infection with C. perfringens resulted in a significant decrease in the frequency of CD3ζ + CD4+ αβ T cells across all segments of the intestine." (PMID 38164397, 2023). "HIV infection results in a reduction in the count of CD4+ lymphocytes, and once this number drops below a certain threshold, patients become vulnerable to secondary infections." (PMID 37606452, 2023). "Similar to their germline knockout counterparts, Bhlhe40fl/fl-Cd4-cre mice showed a significant difference in their ability to control their infection compared to the control Bhlhe40fl/fl mice." (PMID 37843306, 2023). "The early pathogenesis of MDV includes a lytic infection in B cells, followed by a latent infection in activated CD4+ T cells." (PMID 36992357, 2023). "The carbohydrate recognition domain of Gal-3 interacts with HIV-1 gp120 or CD4 molecules, triggering the formation of Gal-3 oligomers, which facilitate infection." (PMID 37298569, 2023). "At 1-month post-infection, we observed a median of 0.49% and 0.18% for CD4 + and CD8 + T cells, respectively, using the S-small pool." (PMID 37974069, 2023). "After infection with coxsackievirus B3, CD4+ T cells from male animals predominantly produced the Th1 cytokine IFN-gamma, whereas those from females produced the Th2 cytokine IL-4." (PMID 38140610, 2023). "Breakthrough infection significantly increased both CD4+ and CD8+ T-cell frequencies, to comparable levels in older and younger adults." (PMID 38035132, 2023). "The proportion of CXCR3+CCR5+ CD4 T cells remained constant with infection, while there was a relative decline in these cells in the spleen during the acute phase." (PMID 38060615, 2023). "Similar to our primary infection studies, pregnant macaques at late first / early second trimester gestation were subjected to CD4+ T lymphocyte depletion and then inoculated with RhCMV virus strains." (PMID 37796819, 2023). "Some studies have indicated that CD4+ TRM cells can provide strong protection against a lethal challenge infection with a heterosubtypic influenza virus strain or play a dominant role in the initiation of antitumor immunity." (PMID 37154735, 2023). "To incorporate these conflicting influences, we developed a measure of virulence—the ‘rate of disease progression’—that depends on both the decline of CD4+ T cells and their level immediately after primary infection." (PMID 37161335, 2023). "In the current study, we found that IL-17+ and IFNγ+ T cells (mainly CD4+) are expanded in higher numbers following infection with Δhla, compared with WT." (PMID 36693884, 2023). "Peripheral T follicular helper (pTfh) cells are a subset of CD4+ T cells that are transiently found in the periphery following vaccination or infection and robustly correlate with induction of Ab responses." (PMID 37104041, 2023). "Infection with HP in adults increases the number of CD4+ T cells and induces the activation of CD4+ and CD8+ T cells." (PMID 37138564, 2023). "We cannot exclude that memory triple or double cytokine+ CD4 T cells differentiate into single IFN‐γ+ during the re‐infection." (PMID 37490492, 2023). "Several factors can regulate the susceptibility to HIV during infection, such as the cell’s metabolic activity, activation stage, and glycolytic enzymes, where elevated glycolysis and OXPHOS favor infection in CD4+ T cells." (PMID 36695947, 2023).
infection (continued). "We found that CD4+ T cells from Emu-infected mice at day 90 post-infection were oriented towards a Treg pathway (CD4+CD25+) at either spleen or colon site." (PMID 37355675, 2023). "Longitudinal studies using the QVOA in people with HIV (PWH) on suppressive ART revealed that the half-life of the latent reservoir in resting CD4+ T cells is 44 mo, long enough to ensure lifelong persistence of the infection even with optimal ART." (PMID 37844236, 2023). "Substantial differences were observed after 30 days of infection, when there was an elevation of CD4+ IFN-γ+ T cells in the animals vaccinated with DNA TS/ASP + Ad TS/ASP, and a robust increase of CD8+ IFN-γ+ T cells in both immunized groups." (PMID 37258518, 2023). "B cells, by virtue of their multifunctionality, play an important role in modulating CD4+ T cell responses in a range of immunological reactions, including those arising from infection." (PMID 36888692, 2023). "The degree of the alterations correlated with the severity of infection, with lower CD4 cell count observed among subjects exhibiting the highest brain metabolic alterations." (PMID 36937663, 2023). "Results showed that the CD4+ T cell apoptosis (Annexin-V+) was significantly reduced on days 5 and 9 of the LdMIF−/− infection compared to LdWT infection (respectively) corresponding to the expansion phase of the T cell responses post-infection." (PMID 37147351, 2023). "Infections in chimpanzees revealed that CD4+ T cells were the dominant T cell response during HAV infection and more heavily correlated with clearance than CD8+ T cells." (PMID 36992265, 2023). "This is in support with other studies that reported an increase in lung CD4 T cells expressing Rora after infection and allergens, including ragweed pollen, papain, and OVA." (PMID 37387671, 2023). "In this study, we used CD4% as a surrogate marker of disease progression since the estimated date of infection was only known for seven of the individuals." (PMID 36366545, 2022). "The two means for the establishment of viral latency consist of direct infections in CD4+ TRM cells and cell-to-cell transmission between infected and uninfected CD4+ TRM cells." (PMID 35664434, 2022). "Retroviral RT is the primary key factor in the successful replication of the virus following the infection of target cells, such as macrophages and CD4+ T cells." (PMID 35893688, 2022). "The model for adult infection, with θ(t, T) = λ − dTT, was a poor fit to the infant data, particularly the CD4 T cell counts." (PMID 35969641, 2022). "CD4+ TNF expression was significantly lower in persistent infection compared to active infection (p=0.0058) as was CD4+ EGR2 (p=0.020)." (PMID 36439147, 2022). "The level of CD8+ T cell response decreases to almost half when compared to CD4+ after 6 months of infection." (PMID 35891232, 2022). "We infected mice with BCG plus either HK-BCG or HK-Msm and determined antigen-specific CD4+ T cell response and bacterial burden at 2 weeks post-infection." (PMID 36104771, 2022). "Upon introduction of CD127 to determine T‐bet expression in effector cells (CD44+CD127−), pup effector CD4+ T cells expressed significantly higher levels of T‐bet after infection." (PMID 36131528, 2022). "The sort-selected DCs were cultured with CFSE-labeled CD4+ T cells isolated from the spleens of mice previously infected with L. donovani and recovered from infection." (PMID 35192633, 2022). "As expected, infected cells were most frequent during acute infection, when ~40% of all memory CD4 T cells fell into one of the three infection classes." (PMID 35510859, 2022). "Infection also induces higher frequencies of CD4+ T cells with increased functional capacity than are induced by inactivated vaccine." (PMID 35336877, 2022). "A study has shown that CD8 T cells significantly decreased while CD4/CD8 ratio significantly increased in VTE patients complicated with infection." (PMID 35681174, 2022).
infection (continued). "Antigen-specific CD4+ T cells expand upon pathogen recognition and, depending on the infection milieu, differentiate into distinct effector cell types, including T helper 1 (Th1), Th2, Th17, T follicular helper (Tfh), and T regulatory (Treg) cells." (PMID 35858332, 2022). "Among HIV infected individuals with functional defects in CD4 cell responses, S. aureus can demonstrate infection which is beyond colonization." (PMID 36962756, 2022). "In humans, higher frequencies of M. tuberculosis specific CD153+ CD4 T cells correlate with a lower lung bacterial load, and Tnfsf8-/- mice have earlier mortality than wild-type following infection." (PMID 35877763, 2022). "Intracellular cytokine staining was also performed at week 62 post-infection to determine SIV-specific CD4+ and CD8+ T cell responses following vaccination." (PMID 35585080, 2022). "Ability to produce IFN-γ can be used as a marker of lymphocyte function, Th1 CD4 effector T cells can produce large amounts of IFN-γ to fight the infection of intracellular pathogens, thereby stimulating and maintaining effective cellular immune responses." (PMID 35720307, 2022). "This was not due to competition between naive and memory cells, because the same effect was observed when CD45RA+ and CD45RA− resting CD4+ target T cells were separated prior to cell-to-cell infection." (PMID 35417711, 2022). "Twenty-one days post infection, CD4+ T lymphocytes were evaluated and compared among the different infected groups." (PMID 35456728, 2022). "Genuine M-tropic viruses are thought to emerge through adaptation to body niches where MΦ or related cells are present in a context of CD4+ T-cell paucity, in particular at the late stage of infection when the CD4 T-cell count declines." (PMID 35622876, 2022). "Assessment of CD25+Foxp3- CD4+ T cells, representing activated effector CD4+ T cells populations, revealed their numerical and proportional expansion in the liver from wk 8 of infection." (PMID 35958580, 2022). "About 2–3 weeks after infection, a T-cell response (both CD4+ and CD8+) leads to the granuloma formation." (PMID 36160177, 2022). "coli was significantly lower than that in group DIO-uninfected at 12, 24, and 72 h post-infection (p < 0.01), the percentage of CD4+T cells in group DIO-E." (PMID 35720836, 2022). "Insufficient protection of alveolar macrophages to the infection will initiate adaptive immunity and activate lymphocytes (T cells), which then induce apoptosis (upregulated Caspase-3 and downregulated CD4 T-cells)." (PMID 35786088, 2022). "As was seen with the HCMV-infected DCs, CD4 T cells control infection in RPE cells via both cytokines (IFN-γ) and cytolytic mechanisms." (PMID 36445084, 2022). "Inducing the immune response of CD4 T-cells using the epitopes of these proteins protects against infection." (PMID 35400957, 2022). "Mild/asymptomatic infection appears to establish stable, responsive CD4+ and CD8+ memory T cells that potentially provide protection against severe illness." (PMID 36271095, 2022). "The inhibitory activity of SAMHD1 on HIV-1 replication has been also reported in the case of the infection of resting CD4+ T lymphocytes." (PMID 35328442, 2022). "Intravital imaging studies demonstrated that cDC1s serve as a communication link between CD4+ and CD8+ T cells on the second day after infection, simultaneously engaging cells from both lineages and facilitating CD4+ T cell help to the CD8+ T cell response." (PMID 35911755, 2022). "Within lymphoid cells, we noted higher expression of the activation marker CD69 on CD4+ T cells at day 7 in severe/critical disease compared to either pre-infection or mild/moderate disease." (PMID 36522333, 2022). "Previous studies showed that Gal-1 promotes the interaction between the viral envelope glycoprotein (gp120) and the cellular receptor CD4, thus facilitating virus attachment and infection." (PMID 35943163, 2022).
infection (continued). "In natural infections, antigen-specific CD4+ T cells are generated, and clinical trials show that the CD4 response persists for three years after vaccination." (PMID 36077216, 2022). "Two weeks following the primary infection, flow cytometry analysis of blood immune cells showed that spike-specific B cells and CD4+ T cells were significantly elevated in the blood of SCFA-treated mice." (PMID 35915556, 2022). "In the presence of infection or inflammation, the initial CD4+ T cells differentiate into Th17 cells, thereby inducing a chronic inflammatory response." (PMID 35733131, 2022). "Another study reviewing post-operative infection rates in HIV positive patients showed that patients with lower preoperative CD4+ counts were more likely to develop SSIs following abdominal surgery." (PMID 35442982, 2022). "The higher abundance of the cell adhesion molecule LFA-1 on BALF CD4+ T cells from diseased animals indicates the higher presence of CD4+ T cells that are antigen specific and expanded due to infection." (PMID 36131278, 2022). "HIV preferentially replicates in activated CD4+ T cells, whereas resting CD4+ T cells demonstrate relative resistance to infection, particularly in vitro." (PMID 34465136, 2022). "A remarkable increase in the expression of CD4+ICOS+Foxp3+ regulatory T cells on 10th day post infection was observed during lethal (P. berghei and P. yoelii 17XL) infection." (PMID 35109868, 2022). "Sialic acid on gp120 is recognized by multiple members of the Siglec family of lectins, and these lectins can facilitate trans- or cell-to-cell infection of CD4+ T cells." (PMID 35787792, 2022). "The presence of neutralizing antibodies (IgG) suggests that both humoral and CD4+ cellular immune responses are activated during infection." (PMID 36611767, 2022). "(F) Frequency of dead target cells (LPS-induced B cell blasts) in cytotoxic assay, after 14 hr of co-culture with CD4+CD44hi T cells sorted from WT (blue line) or Il18ra-/- (red line) infected mice at day 13 post-infection (pi)." (PMID 35670567, 2022). "A strong correlation was found between CXCR4 internalization defect and severity of blood leukocytopenias and infection susceptibility, and between AKT activation and immunoglobulin A level and CD4+ T-cell counts." (PMID 36089616, 2022). "During Cl13 infection, Selplg-/- CD4+ and CD8+ T cells increased at early stages of Cl13 infection, however, these cells eventually decreased to lower levels than those of WT T cells at later stages of chronic infection." (PMID 35774790, 2022). "The number of IFNγ+ CD4+ T cells was also higher in LY‐411,575‐treated lungs but similar in LNs when the infection was established after day 7 PI." (PMID 35603470, 2022). "After infection, naïve CD4 T cells mature into Th1, Th2, Th17, Tfh, or Treg lineages that can help or impede other immune cells to kill microbes." (PMID 35196366, 2022). "IRIS is an inappropriate inflammatory response to an infection that occurs in severely immunocompromised PLHIV (CD4 cell count < 200/mm3) within the first six months of HAART initiation." (PMID 35245291, 2022). "It is well known that some CD8+ T cells are dependent on CD4+ T cells to perform their functions during infection." (PMID 36046744, 2022). "By implementing PP-SLIDE to discern antigens differentially expressed as a result of remodeling from those differentially expressed as a reflection of HIV selection, we found that both fucose and sialic acid were upregulated on CD4+ T cells after infection." (PMID 35787792, 2022). "Although clinical infection of the virus has been shown to drastically deplete CD4+ and CD8+ within the first 21 dpi their inclusion in vaccine design is essential to induce lasting humoral responses." (PMID 35891436, 2022). "In the case of crude extracts on CD4+ T cells, the levels of p24 antigen in the virus culture supernatants ranged from 0.1 to 34.6 μg/ml upon infection." (PMID 36583026, 2022).